ENSG00000283321 (novel protein)
Gene: Protein-coding gene on chromosome 7 (17,299,295 to 17,467,234, forward strand). Ensembl gene ENSG00000283321.
Genetic constraint (gnomAD): Loss-of-function variants: 30 observed, 71.6 expected, observed/expected ratio (o/e) 0.42, 90% interval 0.31 to 0.57. Missense variants: 858 observed, 903.47 expected, observed/expected ratio (o/e) 0.95, 90% interval 0.9 to 1. Synonymous variants: 332 observed, 312.9 expected, observed/expected ratio (o/e) 1.06, 90% interval 0.97 to 1.16.